MAGEA9 (MAGE family member A9)
Description:
Not known, though may play a role in embryonal development and tumor transformation or aspects of tumor progression.
Synonyms: CT1.9; MAGE9; MGC8421
Tractability: PROTAC: ubiquitination databases record sites on it.
Gene: Protein-coding gene on chromosome X (149,781,930 to 149,787,737, forward strand). Ensembl gene ENSG00000123584.
Subcellular location (Human Protein Atlas): Golgi apparatus; Nucleoplasm
Gene Ontology:
Molecular function: protein binding; histone deacetylase binding
Biological process: negative regulation of transcription by RNA polymerase II
Cellular component: nucleus
Homologues: Orthologues: macaque MAGEA9 (90% identical), zebrafish ndnl2 (21% identical), Drosophila melanogaster MAGE (17% identical). Paralogues in human: MAGEA9B (100% identical), MAGEA8 (67% identical), MAGEA4 (65% identical), MAGEA1 (61% identical), MAGEA11 (60% identical), MAGEA3 (59% identical), MAGEA12 (59% identical), MAGEA2 (59% identical), MAGEA2B (59% identical), MAGEA6 (58% identical), MAGEA10 (53% identical), MAGEB16 (47% identical), and 25 more.
Diseases named in the same sentence as MAGEA9 in open-access papers:
MAGEA9 is named in the same sentence as 25 diseases in open-access papers, as found by Europe PMC text mining. Sharing a sentence is not in itself a finding about the gene and the disease. The quoted sentences say what the papers report.
bladder cancer (4 papers, 2015 to 2024). "MAGEA4 expression in these tumors was associated with progression to MIBC (HR = 7.417, p = 0.013) based on univariate analyses, whereas MAGEA9 expression was further predictive of bladder cancer progression." (PMID 38254738, 2024). "MAGEA9 is frequently overexpressed in bladder cancer, cutaneous T-cell lymphomas, oesophageal adenocarcinomas, as well as in renal cell carcinoma." (PMID 31877723, 2019).
renal cell carcinoma (4 papers, 2015 to 2022). "Overexpression of MAGEA9 correlates with unfavorable survival in lung adenocarcinoma, renal cell carcinoma, and esophageal adenocarcinomas, amongst many other tissues’ cancer." (PMID 36430456, 2022).
melanoma (3 papers, 2021 to 2025). A malignant, usually aggressive tumor composed of atypical, neoplastic melanocytes. "We continued to assess the effect of DAC treatment on the expression of MAGEA1, MAGEA3/MAGEA6, and MAGEA9 in a broad panel consisting of 37 cell lines originating from female reproductive organ tumors, melanoma, hematopoietic, or other cancers." (PMID 40791813, 2025). "For example, MAGEA1 is upregulated in lung cancer, melanoma, and gastric cancer; MAGEA3 is upregulated in breast and lung cancer; MAGEA4 is upregulated in melanoma; MAGEA5 is upregulated in head and neck cancer; and MAGEA9 is upregulated in liver and colon cancer." (PMID 34202157, 2021).
non-small cell lung carcinoma (3 papers, 2021 to 2023). A group of at least three distinct histological types of lung cancer, including non-small cell squamous cell carcinoma, adenocarcinoma, and large cell carcinoma. "For example, in non-small cell lung cancer, the expression of MAGEA9 is significantly correlated with decreased survival rate." (PMID 34737950, 2021).
ovarian tumor (1 paper, 2023). "For ovarian tumor samples, we detected six hub genes: GAGE2A, GAGE1, MAGEA9, CTAG1A, CTAG1B, and MAGEA1." (PMID 37835834, 2023).
tumor (16 papers, 2015 to 2025). "In summary, DAC treatment can substantially induce or enhance the reactivity of MAGEA1-, MAGEA3/A6-, and MAGEA9-specific TCR T cells toward diverse tumor cell lines." (PMID 40791813, 2025). "MAGEA9 showed the strongest induction in healthy B cells and T cells, reaching relative expression levels that were comparable or even higher than in the tumor cells tested." (PMID 40791813, 2025). "It should be noted that only the MAGEA9 gene was common for the co-expression networks of CTAs mRNAs among tumor and healthy ovarian tissue." (PMID 37835834, 2023). "Among the DEGs identified in both subtypes, MAGEA9 showed the greatest upregulation in tumour tissues." (PMID 31877723, 2019). "LOC100363492 (Ly6k), MGC114427 (Magea9), and Mageb1 are known as tumor antigens and were all expressed at a lower level in MLL- than in AT1-tumors, especially Ly6k." (PMID 28472073, 2017). "To assess whether MAGE genes were induced to levels that could be relevant for T-cell-mediated recognition, we compared the relative expression levels of MAGEA1, MAGEA3/MAGEA6, and MAGEA9 after DAC induction in healthy cells to the relative expression levels in tumor cells." (PMID 40791813, 2025). "MAGEA9 has been speculated to function as an oncoprotein and to favor tumor cell survival." (PMID 36430456, 2022). "DAC treatment of tumor cells again resulted in the induction of MAGEA1, MAGEA3/MAGEA6, or MAGEA9 expression as validated by qPCR." (PMID 40791813, 2025). "Strong anti-tumor reactivity of the CTA-specific TCR T cells against different tumor cell lines correlated with markedly induced expression of MAGEA1, MAGEA3/A6, and MAGEA9 by DAC treatment." (PMID 40791813, 2025). "CT47A1, PAGE1, MAGEA9, MAGEC2, and MAGEA1 were detected at protein level in tumor tissues (CT47A1 in 14%, PAGE1 in 23%, MAGEA9 in 11%, MAGEC2 in 59% and MAGEA1 in 34% of tumors)." (PMID 34065388, 2021). "We identified six TAA protHLAIp that were exclusively detected in the tumor tissue of C3N-02289 (BIRC5, TERT, FAP, SPAG4, MAGEA9, and BCL2L1)." (PMID 32157095, 2020). "The examination indicated the hub genes in tumor samples, including GAGE2A, GAGE1, MAGEA9, CTAG1A, CTAG1B, and MAGEA1; and the hub genes in healthy ovarian tissue samples, including SPA17, MAGEC1, KDM5B, SSX4, and MAGEA9." (PMID 37835834, 2023).
cancer (8 papers, 2015 to 2025). A tumor composed of atypical neoplastic, often pleomorphic cells that invade other tissues. "While extensive interactions between MAGE family genes such as MAGEA9, MAGE9B, MAGEB6 and MAGEC1 correspond to the cancer subtypes BLCA, HNSC and LUSC, interactions between Zinc fingers C2H2-type proteins in the downregulated components characterized COAD and READ cancer subtypes." (PMID 34728699, 2021).
MAGEA9 also shares sentences with these, for which no sentence is quoted: breast carcinoma (6 papers); hepatocellular carcinoma (3); ovarian carcinoma (3); cutaneous T cell lymphomas (2); esophageal adenocarcinoma (2); gastric cancer (2); lung adenocarcinoma (2); lung carcinoma (2); lymph node metastasis (2); benign tumor (1); cervical cancer (1); colon carcinoma (1); esophageal cancer (1); female reproductive organ tumors (1); head and neck squamous cell carcinoma (1); laryngeal squamous cell carcinoma (1); Lung squamous cell carcinoma (1); ovarian epithelial tumor (1).